CD33 (CD33 molecule)
Diseases named in the same sentence as CD33 in open-access papers (continued):
Sharing a sentence is not in itself a finding about the gene and the disease.
colon cancer (8 papers, 2013 to 2024). "Among the human CD-33-related Siglecs, the engagement of Siglec-7 and Siglec-9 was confirmed in growth and progression of breast, pancreas and colon cancers." (PMID 33670244, 2021). "To assess the value of these findings, we next analyzed the expression of perforin and GzmB in M-MDSCs (CD11b+CD33+CD14+HLA-DRlow) and PMN-MDSCs (CD11b+CD33+CD15+) of colon cancer patients and healthy donors." (PMID 31212684, 2019). "Previous studies have described significant increase in circulating Lin−/HLADR−/CD11b+CD33+ MDSCs in the peripheral blood of patients with advanced cancer including colon cancer." (PMID 25823653, 2015). "Previous work established the presence of the Lin−/lowHLA-DR−CD11b+CD33+ circulating MDSCs in the blood from colon cancer patients that suppressed T cell proliferation and cytokine production 27]." (PMID 23437326, 2013). "In patients with colon cancer, MDSCs have recently been described as Lin−/lowHLA-DR−CD11b+CD33+ cells correlating with cancer stage, metastasis and chemotherapy response." (PMID 23437326, 2013). "In addition, a population with Lin−/lowHLA-DR−CD11b+CD33+ phenotype has been demonstrated to have the features and properties of MDSCs in the blood from patients with glioblastoma, breast cancer, colon cancer, lung cancer or kidney cancer 15,26–29]." (PMID 23437326, 2013).
diabetes (8 papers, 2012 to 2024). "CD33+HLA-DR-/low MDSCs are associated with other complications of diabetics such as hypertension and cardiovascular markers of the disease (cLDL)." (PMID 31915708, 2019). "According to these authors, these data support the importance of blood glucose control for innate immune function and suggest the participation of CD33 in the inflammatory profile associated with diabetes." (PMID 25922592, 2015). "However, the role of CD33 in the inflammation associated with hyperglycemia and diabetes is unknown." (PMID 22500980, 2012). "One study found that patients with type 1 diabetes mellitus (T1D) have significantly greater numbers of MDSCs in their peripheral blood with M-MDSCs (CD14+ CD33+ HLA-DR−) being the most prevalent subset of MDSCs." (PMID 39290701, 2024). "In this paper, the role of Siglec-7 in diabetes has been further investigated in-vivo due to the high inter-species variation in the structure and function of CD33-related siglecs." (PMID 28378743, 2017). "Additionally, the relative amounts of CD33+% (ds = −1.0) were adversely impacted in septic patients with diabetes and obesity." (PMID 36687421, 2022). "We observed that the percentage of CD33+ monocytes was significantly diminished in septic shock patients with or without diabetes." (PMID 36687421, 2022). "Furthermore, the spontaneous production of IL-6 by CD33-/lowplasmacytoid dendritic cells from patients with diabetes without atherosclerotic complications has been reported." (PMID 22500980, 2012).
pancreatic cancer (8 papers, 2014 to 2024). "In accordance, CD33+ myeloid cells isolated in the postoperative phase of pancreatic cancer surgery produced higher ROS levels, compared with healthy donor myeloid cells." (PMID 38598844, 2024). "To test whether the observations are reproducible in human MDSCs, we isolated cells that were double-positive for CD11b and CD33, which are well-known markers of MDSCs, from human PBMCs derived from pancreatic cancer patients." (PMID 27322081, 2016). "For patients with pancreatic cancer, release of S100A8/A9 proteins from myeloid cells increases CD33+CD14−HLA-DR− myeloid-derived suppressor cells." (PMID 30558665, 2018). "The genes overexpressed in the PDL1-up group of pancreatic cancers also included CD33, but not CD14, which is concordant with the presence of myeloid-derived suppressor cells (MDSCs)." (PMID 27589570, 2016). "Third, we found upregulation of the CD33 transcript, but not of CD14, suggesting the presence of myeloid-derived suppressor cells (MDSCs), previously reported as increased in pancreatic cancer." (PMID 27589570, 2016).
renal cell carcinoma (8 papers, 2011 to 2022). "In particular, high CD66b, high CD45RO and low CD33 expression are all consistent with mature granulocyte staining, and concur with the mature neutrophil phenotype described in renal cell carcinoma patients and in patients with other advanced cancers." (PMID 25084831, 2014). "Head and neck, cervical/ovarian, colorectal, and renal cell carcinoma cell lines frequently induced CD33+ MDSC and are good models for further studies of this suppressive population." (PMID 21658270, 2011). "A clinical trial in renal cell carcinoma (RCC) demonstrated that ATRA treatment reduced total CD33+ MDSCs, and induced a stable disease in the majority of patients." (PMID 35158779, 2022). "The results showed that MDSCs like cells, defined as CD11b+CD33+ cells in our study, are located in kidney tissues of patients with lupus nephritis whereas not in healthy kidney area of patients with renal cell carcinoma." (PMID 33986739, 2021). "Decrease in the Lin−/CD11b+/CD33+ monocyte subset was significantly correlated with improved PFS, which was also seen in other cancer settings, and was a particularly suppressive subset examined in renal cell carcinoma and sarcoma patients." (PMID 24498358, 2014).
Cognitive impairment (7 papers, 2014 to 2025). Abnormal cognition is characterized by deficits in thinking, reasoning, or remembering. "Nevertheless, the link between viral hepatitis-induced CD33 activation and cognitive impairment is poorly understood." (PMID 40637125, 2025). "Our approach, called iVAMBN, resulted in a quantitative model that allowed us to simulate a down-expression of the putative drug target CD33, including potential impact on cognitive impairment and brain pathophysiology." (PMID 36780558, 2023). "More recently, the AD field has shifted its focus toward molecular targets (e.g., TREM2 and CD33) aimed at preventing β-amyloid and tau pathologies in presymptomatic patients before cognitive impairment occurs or in patients with mild cognitive impairment before irreversible neuronal damage occurs." (PMID 32370229, 2020). "We will determine whether the peripheral surgical wounding without the influence of general anesthesia can still induce cognitive impairment in aged TNF-α, IL-6, or CD33 knockout mice in our future studies." (PMID 24796537, 2014).
Hodgkins lymphoma (7 papers, 2016 to 2022). A heterogeneous group of malignant lymphoid neoplasms of B-cell origin characterized histologically by the presence of Hodgkin and Reed-Sternberg (HRS) cells in the vast majority of cases. "These are generated to bind CD16 on NK cells and one or two tumor antigens such as CD19 and CD20 (B-cell non-Hodgkin’s lymphoma), CD33 or CD33 and CD123 (AML), CD30 (Hodgkin’s lymphoma), EGFR or EpCAM (EGFR/EpCAM overexpressing carcinomas), and many others." (PMID 28405194, 2017).
Hyperglycemia (7 papers, 2012 to 2023). An increased concentration of glucose in the blood. "On the other hand, a high sugar intake may induce hyperglycemia which is associated with spontaneous TNF-α secretion by peripheral monocytes due to downregulation of the CD33 membrane receptor that is responsible for inhibiting cytokine production." (PMID 30200631, 2018). "Recently, the decreased expression of CD33 has been described in the macrophages of diabetic patients with hyperglycemia." (PMID 23533689, 2013). "Our results suggest that hyperglycemia down-regulates CD33 expression and triggers the spontaneous secretion of TNF-α by peripheral monocytes." (PMID 22500980, 2012). "Preliminary studies in our research group demonstrated that oxidative stress induced by hyperglycemia decreases CD33 expression in human monocytes, but the pretreatment with the antioxidant α-tocopherol prevents ROS production and alteration in the CD33 expression." (PMID 23533689, 2013). "The precise mechanisms by which hyperglycemia down-regulates CD33 expression have not yet been elucidated, although the generation of ROS by high glucose concentrations is believed to contribute to hyperglycemia-induced inflammatory responses." (PMID 22500980, 2012). "Interestingly, the role of CD33 in the production of pro-inflammatory cytokines secondary to hyperglycemia has not yet been explored." (PMID 22500980, 2012).
neutropenia (7 papers, 2021 to 2025). A decrease in the number of neutrophils found in the blood. "In AML, CD33 CAR-T cells target HSPCs and CD33-expressing neutrophils, leading to marrow hypoplasia and severe neutropenia, often making HSCT necessary." (PMID 40186066, 2025). "Actually, target monoclonal antibody–mediated neutropenia was reported in a trial with the CD33-specific antibody-drug conjugates gemtuzumab ozogamicin and SGN-33A by directly binding to CD33 on the surface of myeloid progenitor cells." (PMID 37756687, 2023). "Due to its cytotoxic effect on immature myeloid cells, CD33-targeted therapy leads to profound and long-lasting neutropenia and correspondingly, to increased infection incidence." (PMID 33807678, 2021). "However, the expression of CD33 on myeloid progenitor and mature myeloid cells raises concerns about potential myeloablation and resultant prolonged neutropenia, a life-threatening toxicity." (PMID 39893165, 2025). "Given that CD33 is predominantly expressed on myeloblasts, promyelocytes, myelocytes, some metamyelocytes, and monocytes—and generally absent from band forms and mature granulocytes — the suppression of CD33+ cell differentiation could potentially lead to neutropenia." (PMID 38995485, 2024).
non-Hodgkin lymphoma (7 papers, 2015 to 2025). Distinct from Hodgkin lymphoma both morphologically and biologically, non-Hodgkin lymphoma (NHL) is characterized by the absence of Reed-Sternberg cells, can occur at any age, and usually presents as a localized or generalized lymphadenopathy associated with fever and weight loss. "It constitutes an alternative, promising anti-CD33 immunotherapeutic approach that further builds on the clinical approval of anti-CD19 CAR T cells (Kymriah) to treat B-cell acute lymphoblastic leukemia and non-Hodgkin lymphoma." (PMID 31906437, 2020).
non-small cell lung carcinoma (7 papers, 2015 to 2023). A group of at least three distinct histological types of lung cancer, including non-small cell squamous cell carcinoma, adenocarcinoma, and large cell carcinoma. "M-MDSCs (CD33+CD14+IL-4Rα+ cells) are elevated in non-small-cell lung cancer (NSCLC) patients and are S100A9+." (PMID 36831371, 2023). "Tumor infiltration by M2-like CD163+ CD33+ PD-L1+ macrophages was found in tumor biopsies from all non small cell lung cancer (NSCLC) patients exhibiting hyperprogression." (PMID 32033028, 2020). "CD11b+CD33+ cells are reported as MDSCs in peripheral blood of patients with non-small cell lung cancer." (PMID 26078490, 2015).
Parkinson disease (7 papers, 2017 to 2025). A progressive degenerative disorder of the central nervous system characterized by loss of dopamine producing neurons in the substantia nigra and the presence of Lewy bodies in the substantia nigra and locus coeruleus. "Moreover, polymorphism of CD33 was suggested to impact the pathomechanism of multiple sclerosis and Parkinson’s disease." (PMID 36613460, 2022). "Our study investigates the effect of CD33 SNPs on cognitive functions across populations, including those with chronic hepatitis B, chronic hepatitis C, Parkinson’s disease and healthy controls, to elucidate these relationships." (PMID 40637125, 2025). "Despite observing a significant influence of CD33 SNPs on individuals with viral hepatitis, our analysis did not identify any significant differences in cognitive functions among Parkinson’s disease participants with different genotypes." (PMID 40637125, 2025). "This study examined the associations between CD33 SNPs and cognitive functions across diverse cohorts, encompassing healthy individuals and those affected by HBV, HCV and Parkinson’s disease." (PMID 40637125, 2025). "Previous MR studies on Alzheimer’s disease suggest potential causal associations with BIN1, CCL27, C3, CD33, CD4 T cells, GDF-15 and SVEP1, whereas MR studies on Parkinson’s disease suggest a potential causal association with GPNMB, IL-6 and MIP1b." (PMID 37118290, 2022). "This study aims to investigate the effects of CD33 single-nucleotide polymorphisms (SNPs) on cognitive functions across diverse populations, including healthy controls, individuals with chronic HBV or HCV and those diagnosed with Parkinson’s disease." (PMID 40637125, 2025). "The findings above suggest a significant influence of CD33 SNPs on cognitive functions within the cohort of individuals afflicted by chronic viral hepatitis, an impact not observed in the healthy control group or individuals with Parkinson’s disease." (PMID 40637125, 2025). "This suggests that the five CD33 SNPs under investigation (rs12985029, rs3826656, rs3865444, rs12459419 and rs33978622) did not exert a significant impact on the cognitive functions of individuals diagnosed with Parkinson’s disease." (PMID 40637125, 2025). "To examine whether the effect of CD33 SNPs on cognitive functions is specific to individuals with viral hepatitis or common to all neurodegenerative diseases, we recruited individuals diagnosed with Parkinson’s disease into the present study." (PMID 40637125, 2025). "Our research showed a significant influence of CD33 SNPs on cognitive functions in individuals with chronic viral hepatitis, yet this effect was absent in healthy control and Parkinson’s disease cohorts." (PMID 40637125, 2025). "Our analysis revealed that CD33 SNP variations had no significant cognitive impact on healthy individuals or Parkinson’s disease patients." (PMID 40637125, 2025). "CD33 SNPs were found to have significant effects on immediate recall of logical memory, specifically within the HBV (q = 0.022) and HCV (q = 0.008) cohorts, while no such effects were observed in the healthy control (q = 0.314) or Parkinson’s disease groups (q = 0.222)." (PMID 40637125, 2025). "In this study, we observed an augmented influence of CD33 SNPs in the presence of chronic HBV and HCV infections, an effect not observed in Parkinson’s disease, the second most prevalent neurodegenerative disorder." (PMID 40637125, 2025). "In summary, by integrating neuropsychological assessments spanning multiple cognitive domains with genotypic analyses of CD33 SNPs, we identified a pronounced effect of these in individuals afflicted with chronic HBV and HCV – an effect notably absent in Parkinson’s disease individuals." (PMID 40637125, 2025).
sinusoidal obstruction syndrome (7 papers, 2019 to 2026). "In addition to being present on HSCs, CD33 is also present on hepatic Kupffer cells, which raises the risk of life threatening veno-occlusive disease which has been observed after treatment with gemtuzumab ozogamicin, a monoclonal antibody-drug conjugate against CD33." (PMID 35158765, 2022). "However, similar to the experience with gemtuzumab ozogamicin, an anti-CD33 antibody drug conjugate also linked to calicheamicin, an increased incidence of sinusoidal obstruction syndrome (SOS), previously known as veno-occlusive disease, has been observed with InO." (PMID 30267011, 2019). "CD33- and CD22-targeted ADCs conjugated to calicheamicin, such as GO and InO, are consistently associated with hepatotoxicity and sinusoidal obstruction syndrome." (PMID 41596669, 2026). "CD33 is also expressed on Kupffer cells, and severe hepatic toxicity, including veno-occlusive disease, has been reported with CD33-targeting antibody-drug conjugates, but this toxicity was attributed to the calicheamicin component rather than the targeting of Kupffer cells." (PMID 40186066, 2025). "In addition to hematopoietic cells, CD33 is expressed on hepatic Kupffer cells, raising concerns for its role in hepatic toxicity and sinusoidal obstruction syndrome with previously used CD33-directed therapies." (PMID 32079207, 2020).
viral infection (7 papers, 2020 to 2025). "For example, BIN1 binds to SARS-CoV-2 to block viral infection, whereas CD33 increases SARS-CoV-2 susceptibility and infection severity because of its immunosuppressive effect." (PMID 37962454, 2024). "Previous reports have shown that homeostatic basal levels of plasma CD33 are low but are strongly increased under pathogenic conditions, including viral infections." (PMID 37506557, 2023). "In addition to its effects in viral infections, CD33 has been implicated in neuroinflammation, where its activation reduces phagocytic activity of microglia cells, causing an accumulation of pathogenic Aβ plaques." (PMID 37506557, 2023). "We and others have previously shown that CD11b+CD33+CD14+HLA-DR-/lo monocytic MDSC (M-MDSC) are present in individuals with clinical recovery from viral infection." (PMID 35812392, 2022). "It is possible that severe and chronic peripheral inflammation caused by persistent bacterial or viral infection may enhance certain genetic vulnerabilities for AD, including those conferred by APOE ε4, as well as particular SPI1 and CD33 genotypes." (PMID 36550123, 2022). "To investigate more directly the potential involvement of CD33 in HIV-1 infection and viral reservoir, we tested whether targeting CD33 in vitro on T cells and monocyte-derived macrophages (MDM) would impact viral infection and replication." (PMID 37506557, 2023). "Myeloid/classical DCs (mDCs) express typical myeloid antigens (CD11c, CD13, CD33, CD11b) with the majority of them expressing CD1c/BDCA1, while plasmacytoid DCs (pDCs) express CD123, CD303/BDCA2, CD304/BDCA4, and produces IFNα after activation with CpG or viral infection." (PMID 32676075, 2020).
B cell lymphomas (6 papers, 2017 to 2024). "Most engineered CAR-NK cells are directed against blood-related malignancies, such as CD19 for B cell lymphomas, CD22 for refractory B-cell lymphomas and solid tumors, NKG2D-ligand for pancreatic cancers, and CD33 and ROBO1 specific BiCAR-NK/T for malignant and metastatic solid tumors." (PMID 34925314, 2021).
ovarian carcinoma (6 papers, 2017 to 2025). A malignant neoplasm originating from the surface ovarian epithelium. "To examine whether intratumoral CD33+ cells suppress T cell proliferation, we isolated CD33+ cells from primary ovarian cancer samples and incubated the isolated cells with proliferating T cells." (PMID 29703902, 2018). "To explore the role of MDSCs in EOC, we assessed the frequencies of M-MDSCs (CD11b+CD33+CD14+) and PMN-MDSCs (CD11b+CD33+CD15+) in peripheral blood and tumor tissues from patients with benign and malignant ovarian tumors." (PMID 41029721, 2025). "The overexpression of PGE2 in the microenvironment of ovarian cancer also induces the production of CXCL12 (SDF1), thereby enhances the migration of CD11b+CD14+CD33+CXCR4+MDSCs to the ascites of patients with ovarian cancer." (PMID 34689842, 2021). "Importantly, analogous treatment with scFvFITC:sFasL also markedly triggered apoptosis in 6 out of 7 primary patient-derived ovarian cancer samples when pretargeted with anti-CD44-FITC, but not with anti-CD33-FITC (4 out of 5)." (PMID 29038485, 2017).